TRIP6 (thyroid hormone receptor interactor 6)
Diseases named in the same sentence as TRIP6 in open-access papers (continued):
Sharing a sentence is not in itself a finding about the gene and the disease.
glioma (5 papers, 2018 to 2024). A benign or malignant brain and spinal cord tumor that arises from glial cells (astrocytes, oligodendrocytes, ependymal cells). "The overexpression of TRIP6, which is upregulated in glioma cells and tissues, is associated with unfavorable clinical outcomes among glioma patients." (PMID 38430268, 2024). "TRIP6 had the potential to influence the proliferation and migration of glioma cell, thereby causing unfavorable clinical outcomes." (PMID 39882240, 2024). "In order to investigate the molecular mechanism of LINC00675 involved in glioma tumorigenesis, we observed LINC00675 expression was significantly positively associated with TRIP6 expression in glioma from TCGA database." (PMID 30061182, 2018). "To investigate the molecular mechanism of LINC00675 involved in glioma tumorigenesis, we observed LINC00675 expression was significantly positively associated with TRIP6 expression in glioma from TCGA database (r=0.552, P<0.001)." (PMID 30061182, 2018). "Furthermore, the association of LINC00675 expression with TRIP6 mRNA and protein was further investigated in glioma tissue samples." (PMID 30061182, 2018). "We then conducted TRIP6 knockdown experiments, which successfully reduced TRIP6 expression in all three glioma cell lines." (PMID 39882240, 2024). "In glioma, TRIP6 was overexpressed in all types of gliomas and negatively associated with poor clinical outcomes." (PMID 30061182, 2018). "The in vitro experiment showed that silencing of LINC00675 inhibits glioma cell proliferation, migration and invasion through regulating TRIP6." (PMID 30061182, 2018). "Silencing of LINC00675 inhibits glioma cell proliferation, migration and invasion through regulating TRIP6." (PMID 30061182, 2018). "In addition, we have not conducted in-depth experimental verification on the specific regulatory mechanism of TRIP6 gene on glioma energy metabolism." (PMID 39882240, 2024). "LINC00675 facilitates glioma cell proliferation, migration and invasion through regulating TRIP6." (PMID 34738869, 2021). "TRIP6 expression is up-regulated in glioma cells and tissues and its overexpression is correlated with poor clinical outcomes of glioma patients, which indicates that TRIP6 may become a novel prognostic biomarker and therapeutic target of glioma." (PMID 32082081, 2020). "We did not study the association between TRIP6 gene expression and glioma drug resistance." (PMID 39882240, 2024). "In order to detect the downstream signals of TRIP6 in GBM, RNA sequencing was carried out after silencing TRIP6 expression in glioma cell." (PMID 39882240, 2024). "Thus, LINC00675 might modulate TRIP6 to regulate glioma cell proliferation, migration and invasion." (PMID 30061182, 2018).
gastric cancer (4 papers, 2021 to 2025). A primary or metastatic malignant neoplasm involving the stomach. "The expression of TRIP6 has been shown in gastric cancer but its expression in the two subtypes—diffuse and intestinal—has not been studied." (PMID 34885041, 2021). "Clinical studies to examine the association of mRNA expression of GREM1, BAG2, OLFM4, TRIP6 and MAGE-A9 and OS in patients with intestinal or diffuse subtype of gastric cancer using different chemotherapeutic agents need to be done." (PMID 34885041, 2021). "Overexpression of BAG2, GREM1, OLFM4, and TRIP6 in the diffuse subtype of gastric cancer on IHC as compared to the intestinal subtype suggests a role of these proteins in the pathogenesis and progression of the diffuse subtype." (PMID 34885041, 2021). "TRIP6 has been shown to have a higher expression in poorly differentiated gastric cancer characterized by intense staining on IHC, which decreases with more differentiated forms of gastric cancer." (PMID 34885041, 2021). "These plots suggest Zyxin, LPP, LIMD1, TRIP6, and FBLIM display high levels of mutational frequency in stomach cancer." (PMID 33808029, 2021). "To date, upregulation of the TRIP6 gene occurred in daunorubicin- (EPG85-257RDB) and mitoxantrone-resistant (EPG85-257RNOV) human gastric carcinoma cells, the former cells having also upregulated ABCB1." (PMID 36833223, 2023). "The candidate proteins BAG2, GREM1, OLFM4, TRIP6, and MAGE-A9, were shown to be differentially expressed and validated using IHC in the diffuse and intestinal subtypes of gastric cancer." (PMID 34885041, 2021). "Although GREM1, BAG2, OLFM4, TRIP6 and MAGE-A9 have all been previously implicated in tumor progression and metastasis, they have not been linked to intestinal or diffuse subtypes of gastric cancer." (PMID 34885041, 2021).
glioblastoma (3 papers, 2016 to 2024). The most malignant astrocytic tumor (WHO grade IV). "The regulatory gene network highlights proteinssuch as thyroid receptor-interacting protein 6 (TRIP6), whichis overexpressed in glioblastoma and promotes tumor cellinvasion (Lai Y.-J." (PMID 39944803, 2024). "TRIP6 is significantly overexpressed in glioblastomas with aberrantly elevated c-src activation and is related to the progress of glioblastomas." (PMID 32082081, 2020). "Likewise, in the U373-MG glioblastoma cells that showed constitutive NF-κB activity and high levels of TRIP6, depletion of TRIP6 by Cas9/sgRNA also attenuated the basal and LPA-stimulated IκBα phosphorylation and JNK activation." (PMID 27134758, 2016).
breast tumors (2 papers, 2020 to 2023). "Instead, the analysis of breast tumor of a neoadjuvant cohort revealed TRIP6 mRNA expression level associations with positive progesterone receptor expression status and premenopausal status." (PMID 36833223, 2023). "Whereas all breast tumor tissues expressed TRIP6 mRNA, we detected TRIP6 protein expression by immunoblotting in 17 of the 20 examined samples." (PMID 36833223, 2023). "Consistently, compared with normal tissues, TRIP6 mRNA expression was significantly up-regulated in breast tumors." (PMID 32082081, 2020). "TRIP6 mRNA expression negatively correlated (Spearman’s coefficient = −0.52, p < 0.001) with CpG methylation level, indicating that DNA methylation might regulate TRIP6 expression also in breast tumors." (PMID 36833223, 2023). "Therefore, we aimed to validate this finding by evaluating TRIP6 expression in 95 breast tumor tissue samples and 6 non-tumor tissues collected in the Czech Republic." (PMID 36833223, 2023).
colon cancer (2 papers, 2025). "Comparing the gene expression levels between normal and tumor tissues in colon cancer patients revealed an upregulation of the TRIP6 gene associated with disulfide death." (PMID 40442106, 2025). "Concurrently, our in vitro functional assays independently validated its role as a potent oncogenic factor, demonstrating that silencing TRIP6 significantly suppressed the proliferation, migration, and invasion of colon cancer cells." (PMID 41438741, 2025).
Infertility (2 papers, 2022 to 2025). "Also, menstrual blood serum was characterized as a less invasive source of infertility biomarkers, where EMILIN1, TRIP6, LAMB1, LAMC1, NID1, APOB, APOA4 were detected as the main differences in uIF patients as compared to healthy controls." (PMID 40861859, 2025).
melanoma (2 papers, 2011 to 2025). A malignant, usually aggressive tumor composed of atypical, neoplastic melanocytes. "To test the clinical implication of this immune-suppressed phenotype, we examined the role of TRIP6 in an external cohort of melanoma patients undergoing immunotherapy." (PMID 41438741, 2025).
atherosclerosis (1 paper, 2021). A disease characterized by the build-up of fatty material and calcium deposition in the arterial wall resulting in partial or complete occlusion of the arterial lumen. "TRIP6, PINX1, and ERI1 have notably been associated with blood pressure, triglyceride levels, HDL cholesterol, diabetes mellitus, and atherosclerosis." (PMID 34753499, 2021). "The gene-based association identified genes (TRIP6, PINX1 and ERI1) were significantly associated with expression change in the whole blood and lung and have previously been associated with blood pressure, triglyceride levels, HDL cholesterol, diabetes mellitus and atherosclerosis." (PMID 34753499, 2021).
cervical cancer (1 paper, 2021). A primary or metastatic malignant neoplasm involving the cervix. "The implication of TRIP6 in tumor progression is illustrated by its overexpression in various cancers, including colorectal, hepatocellular, gastric, breast, and cervical cancers." (PMID 34503076, 2021). "Likewise, in cervical cancer cell lines, TRIP6 promotes proliferation and invasiveness through the YAP1 activation." (PMID 34503076, 2021).
colitis (1 paper, 2022). Inflammation of the colon. "Herein, we therefore employed TRIP6-deficient (TRIP6−/−) mice in order to explore the mechanistic importance of TRIP6 in a dextran sodium sulfate (DSS)-induced model of murine colitis." (PMID 34983535, 2022). "Wild-type (TRIP6+/+) mice developed more severe colitis following DSS-mediated disease induction relative to TRIP6−/− mice, as evidenced by more severe colonic inflammation and associated crypt damage." (PMID 34983535, 2022). "Through a series of experiments, we found that TRIP6−/− mice exhibited a less serious disease phenotype relative to TRIP6+/+ mice, consistent with a role for TRIP6 as a regulator of colitis." (PMID 34983535, 2022). "Whether and how TRIP6 regulates colitis, however, remains unknown." (PMID 34983535, 2022). "As such, we herein analyzed the phenotypic characteristics of TRIP6−/− and wild-type (WT; TRIP6+/+) mice in the context of a DSS-induced colitis model system." (PMID 34983535, 2022).
colorectal adenocarcinoma (1 paper, 2025). The most common type of colorectal carcinoma. "In summary, these findings collectively indicate that TRIP6 plays a critical role in promoting the malignant progression of colorectal adenocarcinoma, and its knockdown effectively suppresses tumor cell proliferation, migration, and invasion in vitro." (PMID 41438741, 2025).
colorectal tumors (1 paper, 2020). "TRIP6 promotes cell migration and invasion through Wnt/β‐catenin signaling and was shown to be upregulated in colorectal tumors." (PMID 32615015, 2020).
diabetic nephropathy (1 paper, 2025). "TRIP6 mediates inflammatory response and renal fibrosis in diabetic nephropathy." (PMID 40995516, 2025).
endometrial cancer (1 paper, 2021). Primary or metastatic malignant neoplasm involving the endometrium (mucous membrane that lines the endometrial cavity). "Similarly, Zyxin, LIMD1 and TRIP6 mutations are linked with endometrial cancer." (PMID 33808029, 2021).
Ewing sarcoma (1 paper, 2020). A small round cell tumor that lacks morphologic, immunohistochemical, and electron microscopic evidence of neuroectodermal differentiation. "Experimental suppression of TRIP6 expression impaired the migratory, clonogenic and tumorigenic potential of Ewing sarcoma cell lines." (PMID 32326412, 2020). "In addition, the zyxin-related cell adherence junction protein TRIP6, which is known to activate YAP/TAZ through competition with MOB1 binding of LATS1/2, is highly overexpressed in Ewing sarcoma and associated with a pro-invasive gene signature." (PMID 32326412, 2020).
head/neck cancers (1 paper, 2021). "For bladder, kidney and head/neck cancers, proteins TRIP6, WTIP, and Ajuba, respectively, showed the highest mutational frequency." (PMID 33808029, 2021).
hepatocellular carcinoma (1 paper, 2020). A malignant tumor that arises from hepatocytes. "In addition, TRIP6 plays an important role in promoting the proliferation of hepatocellular carcinoma by increasing the activity of AKT and inhibiting the activity of FOXO3a and may become a new prognostic biomarker and therapeutic target of hepatocellular carcinoma." (PMID 32082081, 2020).
Hydrocephalus (1 paper, 2021). Hydrocephalus is an active distension of the ventricular system of the brain resulting from inadequate passage of CSF from its point of production within the cerebral ventricles to its point of absorption into the systemic circulation. "Thus, it seems that the obstructive hydrocephalus observed upon deletion of TRIP6 is caused by a CSF circulation block in the foramen of Monro (upstream of the 3rd ventricle) and/or in the aqueduct of Sylvius, between the 3rd and 4th ventricle." (PMID 34620853, 2021). "Here, the author’s describe the scaffold protein TRIP6, which promotes the assembly of ciliary proteins required for ciliogenesis, and show that its absence results in hydrocephalus." (PMID 34620853, 2021). "Trip6 deletion in the mouse, reported here, reveals a function in the brain: ependymal and choroid plexus epithelial cells are carrying, unexpectedly, fewer and shorter cilia, are poorly differentiated, and the mice develop hydrocephalus." (PMID 34620853, 2021).
non-Hodgkin ́s Lymphoma (1 paper, 2021). "High expression of TRIP6 led to worse survival of non-Hodgkin ́s Lymphoma (NHL) patients and it is associated with the accelerated proliferation of NHL cells." (PMID 35008510, 2021).
ovarian clear cell cancer (1 paper, 2025). An invasive malignant neoplasm that arises from the ovary and is characterized by a predominance of clear and hobnail malignant epithelial cells. "Interestingly, this phenomenon mirrors the findings in ovarian clear cell carcinoma, where ARID1A mutations are associated with promoter hypermethylation and transcriptional repression of downstream targets such as IRX1, TMEM101, and TRIP6." (PMID 41215803, 2025).
cancer (15 papers, 2016 to 2025). A tumor composed of atypical neoplastic, often pleomorphic cells that invade other tissues. "TRIP6, a multifunctional protein, regulates a multitude of biological processes associated with diverse types of cancer; for example, TRIP6 promotes carcinogenesis by enhancing the malignant proliferation and invasion of cancer cells." (PMID 38430268, 2024). "Pan-cancer analysis confirmed that TRIP6 is significantly upregulated in COAD tumor tissues compared to adjacent normal tissues." (PMID 41438741, 2025). "The biological function and role of TRIP6 in different cancers have been widely investigated in various clinical and biomedical studies." (PMID 38369589, 2024). "The relevance of our functionally valid observation for clinical course of breast and other cancer(s), including eventual utility of TRIP6 as a target for new therapy design, shall be evaluated by follow-up studies." (PMID 36833223, 2023). "TRIP6 has been suggested to be dysregulated in multiple cancers and plays pleiotropic roles in tumor initiation, tumor growth and metastasis." (PMID 30061182, 2018). "TRIP6 functions at a point of convergence of multiple signaling pathways critical for cancer development, including c-Src/ERK, PI3K/AKT and NF-κB." (PMID 27134758, 2016). "Overall, these findings suggest that an increase in immune cells promoting tumor angiogenesis and a decrease in immune cells inhibiting tumor angiogenesis in the TRIP6 high expression group exacerbate the progression of cancer, leading to unfavorable tumor prognosis." (PMID 38369589, 2024). "As a result of these studies, it has become possible to provide valuable insight into the potential role of TRIP6 in cancer progression and metastasis, a role that may be applied to the diagnosis and treatment of cancer." (PMID 38369589, 2024). "A limited number of studies are devoted to regulating TRIP6 expression in cancer." (PMID 36833223, 2023). "Many studies have shown that TRIP6 is involved in various cancers and might play an important role in tumorigenesis and metastasis." (PMID 34885041, 2021). "TRIP6 deregulations in various cancers may have pleiotropic roles in tumor initiation, tumor growth, and metastasis as summarized in Willier." (PMID 35008510, 2021). "However, how is the ability of TRIP6 to induce self-renewal of cancer cells and what is the precise molecular mechanism?" (PMID 32082081, 2020). "PTPN13 is also involved in the regulation of cancer cell migration/invasion via its partner and substrate thyroid hormone receptor interactor 6 (TRIP6, also called ZRP-1) that promotes cell mobility induced by lysophosphatidic acid, and activates Wnt/β-catenin signaling." (PMID 33322542, 2020). "Thus, TRIP6 represents an attractive molecule in cancer research." (PMID 36833223, 2023). "A comprehensive pan-cancer analysis revealed that in COAD, TRIP6 expression is significantly and negatively correlated with both TMB and MSI status." (PMID 41438741, 2025). "In our previous publications, we reported several new molecules potentially involved in the resistance of cancer cells to taxanes, such as ABCC3, CPS1, and TRIP6." (PMID 35008510, 2021). "We saw significant transcriptional changes including the downregulation of key markers like EGR1 and CD24, whose reduced expression is linked to increased invasiveness and drug resistance and identified proteins such as TRIP6 and TRIM29 that enhance (cancer stem cells) CSC-like properties." (PMID 40946111, 2025). "Therefore, it is necessary to further study TRIP6 to elucidate its potential connection with glycolysis, angiogenesis, and immune infiltration in CRC, which will ultimately contribute to the advancement of cancer treatment and improve patient prognosis." (PMID 38369589, 2024).
cancer (continued). "In addition, we detected the mRNA expression of cancer stem cell makers, including c-MYC, CD44 and CD133, and found that their expression were increased in TRIP6-transduced ZR-75-30 and MDA-MB-231 cells but were decreased in TRIP6-silenced cells." (PMID 32082081, 2020). "The specific manifestation is that overexpression of TRIP6 enhanced the LPA-induced cell migration, while in contrast, inhibition of TRIP6 expression suppressed the LPA-induced cell migration, suggesting that TRIP6 may mediate the LPA2-induced cancer cell migration." (PMID 33194756, 2020).